CDC14A (cell division cycle 14A)
Description:
Dual-specificity phosphatase. Required for centrosome separation and productive cytokinesis during cell division. Dephosphorylates SIRT2 around early anaphase. May dephosphorylate the APC subunit FZR1/CDH1, thereby promoting APC-FZR1 dependent degradation of mitotic cyclins and subsequent exit from mitosis. Required for normal hearing.
Synonyms: Cdc14A1; Cdc14A2; cdc14; DFNB105; DFNB32; DFNB35; hCDC14
Tractability: PROTAC: ubiquitination databases record sites on it; a small molecule that binds it is known.
Target class: Enzyme; Phosphatase
Gene: Protein-coding gene on chromosome 1 (100,325,629 to 100,520,277, forward strand). Ensembl gene ENSG00000079335.
Subcellular location: Nucleus; Cytoplasm, cytoskeleton, microtubule organizing center, centrosome; Cytoplasm, cytoskeleton, spindle pole; Cytoplasm, cytoskeleton, spindle; Cell projection, kinocilium; Cell projection, stereocilium
Subcellular location (Human Protein Atlas): Endoplasmic reticulum; Nucleoplasm; Cytosol
Pathways (Reactome):
Cell Cycle: Conversion from APC/C:Cdc20 to APC/C:Cdh1 in late anaphase
Signal Transduction: MAPK6/MAPK4 signaling
Gene Ontology:
Molecular function: protein binding; protein serine/threonine phosphatase activity; protein tyrosine phosphatase activity
Biological process: sensory perception of sound; cilium assembly; microtubule cytoskeleton organization; positive regulation of cytokinesis; regulation of exit from mitosis
Cellular component: centrosome; nucleoplasm; nucleus; cytoplasm; kinociliary basal body; kinocilium; mitotic spindle; nucleolus; spindle pole; stereocilium tip; microtubule organizing center; spindle; stereocilium
Genetic constraint (gnomAD): Loss-of-function variants: 26 observed, 31.63 expected, observed/expected ratio (o/e) 0.82, 90% interval 0.6 to 1.14. The upper end of that interval is the gene's LOEUF score, 1.14, which puts it in group 5 of 6, group 1 being the genes least tolerant of losing a copy. Missense variants: 370 observed, 450.4 expected, observed/expected ratio (o/e) 0.82, 90% interval 0.75 to 0.89. Synonymous variants: 155 observed, 170.37 expected, observed/expected ratio (o/e) 0.91, 90% interval 0.8 to 1.04.
Gene-disease validity (ClinGen):
ClinGen rates the evidence that CDC14A causes each of these diseases.
nonsyndromic genetic hearing loss (autosomal recessive): Definitive. A disease characterized by hearing loss that is not part of a larger syndrome.
hearing impairment and infertile male syndrome (autosomal recessive): Strong. A syndromic genetic deafness characterized by segregation of nonsyndromic hearing loss in females and hearing loss with infertility in males.
Homologues: Orthologues: chimpanzee CDC14A (98% identical), macaque CDC14A (97% identical), guinea pig CDC14A (91% identical), rabbit CDC14A (91% identical), pig CDC14A (87% identical), rat Cdc14a (87% identical), mouse Cdc14a (86% identical), dog CDC14A (86% identical), tropical clawed frog cdc14a (63% identical), zebrafish cdc14ab (58% identical). Paralogues in human: CDC14B (45% identical), CDC14C (42% identical), PTPDC1 (18% identical), PALD1 (15% identical), PTP4A1 (10% identical), PTP4A2 (9% identical), PTP4A3 (9% identical), CDKN3 (8% identical).
Diseases named in the same sentence as CDC14A in open-access papers:
CDC14A is named in the same sentence as 21 diseases in open-access papers, as found by Europe PMC text mining. Sharing a sentence is not in itself a finding about the gene and the disease. The quoted sentences say what the papers report.
deafness (4 papers, 2020 to 2024). An inherited or acquired condition characterized by the complete loss of the ability to hear from one or both ears. "These were further supported by the observations that MAP1B deficiency did not affect the morphologies in middle turns, apex, and basal turns of cochlea of mice, in contrast with those in mice bearing other deafness-causing gene mutations such as CDC14A." (PMID 33268592, 2020). "In GER (CD−M3), Tecta, Pcdh15, and Cdc14a were associated with NSHL, Slitrk6 with deafness and myopia, Pcdh15 with Usher syndrome, Eya1 with branchiootorenal syndrome, Chd7 with CHARGE syndrome, and Cdc14a with hearing impairment and infertile male syndrome." (PMID 39684410, 2024). "A frameshift variant (c.1041dup, p.(Ser348Glnfs*2)) was identified in the deafness gene CDC14A (NM_033312.2, DFNB32) in affected family members of family 6 (IV.1, IV.2) and co-segregated with HL in this family." (PMID 33187236, 2020).
Hearing impairment (4 papers, 2020 to 2025). A decreased magnitude of the sensory perception of sound. "In three previous studies, we detected the GJB2 (MIM 121011) and LRTOMT (MIM 611451) variants and CDC14A (MIM608653) variants implicated in hearing impairment in the Mauritanian population." (PMID 39230647, 2025). "Individuals 10 and 11 had a pathogenic homozygous CDC14A variant (NM_033312.2:c.1421 + 2 T > C, p.Val472Leufs*20) that explains isolated hearing impairment (OMIM #608653)." (PMID 38031187, 2023). "Our findings widen the spectrum of clinically relevant CDC14A mutations that are associated with hearing impairment and reinforce its role within the auditory system." (PMID 31906439, 2020). "The present study functionally characterizes two variants and provides further confirmatory evidence that CDC14A is associated with a rare form of hereditary hearing loss." (PMID 31906439, 2020). "CDC14A encodes the Cell Division Cycle 14A protein and has been associated with autosomal recessive non-syndromic hearing loss (DFNB32), as well as hearing impairment and infertile male syndrome (HIIMS) since 2016." (PMID 31906439, 2020).
male infertility (3 papers, 2020 to 2025). The inability of the male to effect fertilization of an ovum after a specified period of unprotected intercourse. "Since both affected individuals in family 1 are female and the unmarried status of both affected males in family 2, we cannot exclude that the newly identified CDC14A variants would also cause male infertility." (PMID 31906439, 2020). "The paralogue CDC14B may compensate for the loss of some CDC14A functions in vivo, but does not compensate for male infertility and hearing impairment with loss of CDC14A." (PMID 31906439, 2020).
breast carcinoma (2 papers, 2009 to 2012). "CDC14A is located at chromosome band 1p21, a region that has been shown to exhibit loss of heterozygosity in highly differentiated breast carcinoma and malignant mesothelioma." (PMID 22548743, 2012).
Cerebral ischemia (1 paper, 2025). Restriction of arterial blood supply to the brain associated with insufficient oxygenation to support the metabolic requirements of the tissue. "High expression of circRNA CDC14A was revealed in blood and peri-infarct neutrophils and astrocytes in mice after reversible local cerebral ischemia." (PMID 41245147, 2025). "In contrast, silencing circRNA CDC14A reduced cerebral infarction, apoptosis, and neurological deficits induced by local cerebral ischemia." (PMID 41245147, 2025). "Moreover, it was revealed that the concentrations of circRNA FUNDC1, circRNA PDS5B and circRNA CDC14A in blood were significantly increased in patients after cerebral ischemia, and their levels correlated with the infarct size." (PMID 41245147, 2025). "In patients after cerebral ischemia, a significant increase in the expression of circRNA PDS5B in lymphocytes and granulocytes and only in granulocytes for circRNA CDC14A was found, and their levels positively correlated with the infarct volume." (PMID 41245147, 2025).
Infertility (1 paper, 2025). "Studies using mouse models have shown that the absence of CDC14A leads to abnormalities in meiosis, sperm morphology defects, and reduced motility, ultimately resulting in infertility." (PMID 40218458, 2025).
tumor (8 papers, 2006 to 2021). "Human CDC14A shares sequence similarity with the recently identified tumor suppressor, MMAC1/PTEN/TEP1." (PMID 22548743, 2012). "Similarly, based on the correlation with stemness scores and immune socres, we could also draw inferences that CDC14A suppressed tumor progression." (PMID 33828913, 2021). "Thus, CDC14A has been thought to be a tumor suppressor gene." (PMID 22548743, 2012). "Furthermore, the CDC14A and H1F0 protein expression were obtained from The Human Protein Atlas data (HPA), indicating that H1F0 was high staining in tumor cells, while it was medium staining in normal tissues." (PMID 33828913, 2021). "Downregulated genes such as LATS2, CDC14A and CAPN2 are known tumor-suppressive molecules which could enhance cell cycle progression, cell mobility and reduce apoptosis." (PMID 34654826, 2021). "Surprisingly, human CDC14A activity is required to control cell adhesion and migration, since the lack of this phosphatase may induce tumor proliferation and metastasis." (PMID 31225502, 2019).
cancer (5 papers, 2006 to 2019). A tumor composed of atypical neoplastic, often pleomorphic cells that invade other tissues. "Expression of Cdc14A protein in human cancer cell lines as determined by Western blot using anti-hCdc14A antibodies (Ab-2)." (PMID 16784539, 2006). "Indeed, several types of cancer present a down-regulation of CDC14A expression, corroborating the role of this phosphatase in tumorigenesis." (PMID 31225502, 2019). "We analysed cdc14A, that regulates centrosome separation and activates the anaphase promoting complex cdh1/APC, Ndc80/Hec1 (Highly Expressed in Cancer;) a component of APC and Aurora Kinase B, a key regulator of chromosome segregation." (PMID 21187932, 2010).
CDC14A also shares sentences with these, for which no sentence is quoted: infection (5 papers); candidiasis (1); CHARGE syndrome (1); fungal infection (1); gastric cancer (1); hearing impairment and infertile male syndrome (1); hepatocellular carcinoma (1); ischemic stroke (1); malignant mesothelioma (1); myopia (1); non-small cell lung carcinoma (1); Sensorineural Hearing Loss (1); Usher syndrome (1).